COL1A1 (collagen type I alpha 1 chain)
Diseases named in the same sentence as COL1A1 in open-access papers (continued):
Sharing a sentence is not in itself a finding about the gene and the disease.
glioma (continued). "Furthermore, to determine whether Col1a1 downregulation within glioma cells modifies the glioma TME we analyzed changes in tumor-associated macrophages (TAM), endothelial cells, and mesenchymal cells." (PMID 35750880, 2022). "Additionally, the top Kyoto Encyclopedia of Genes and Genomes (KEGG) pathways associated with COL1A1, ITGB1, THY1, and PDGFRA genes included pathways such as “ECM receptor interaction, leukocyte transendothelial migration, platelet activation, focal adhesion, and glioma” among others." (PMID 40817072, 2025). "Here, we detailed the highly altered proteins (COL1A1, FN1, VTN, etc.)and the phosphosite (FN1_T1642) in the extracellular matrix (ECM) of BrM, as compared to primary brain tumor gliomas." (PMID 39716938, 2025). "Higher expression of COL1A1, COL1A2, COL3A1, COL4A1, COL4A2, and COL5A2 was negatively correlated with the prognosis of glioma patients." (PMID 38969910, 2024). "Correspondingly, human GBM glioma tumors (IDH1-WT) with high oncostream densities showed prominent alignment of collagen fibers along these fascicles and higher COL1A1 expression compared to LGG (IDH1-Mut)." (PMID 35750880, 2022). "FN1, COL1A1, COL6A1, and LTBP1 were significantly expressed in GBM compared with WHO grade II and III glioma." (PMID 34638384, 2021). "On the CGGA website (mRNAseq_325), collagen genes (COL1A1, COL1A2, COL3A1, COL4A1, COL4A2, and COL5A2) in WHO grades II, III, and IV glioma samples were analyzed to explore the expression levels of these genes." (PMID 34034744, 2021). "Then, six collagen genes (COL1A1, COL1A2, COL3A1, COL4A1, COL4A2, and COL5A2) were selected for further validation in Oncomine, TCGA (The Cancer Genome Atlas), and CGGA (Chinese Glioma Genome Atlas) database." (PMID 34034744, 2021). "Specifically, LSM2 depletion resulted in the upregulation of extracellular matrix (ECM) genes like FN1 and COL1A1, which could disrupt tumour cell-ECM interactions and potentially diminish the invasive phenotypes of glioma cells." (PMID 40365337, 2025). "In particular, several collagen-related genes (e.g., COL1A1, COL3A1, COL5A1) were significantly upregulated, suggesting increased extracellular matrix deposition and the establishment of an immunosuppressive microenvironment in Grade 4 gliomas." (PMID 41432874, 2025). "In detail, COL1A1, COL1A2, COL3A1, COL4A1, and COL4A2 positively correlated with the infiltration of B cells, CD8+T cells, CD4+T cells, macrophages, neutrophils, and dendritic cells in low-grade glioma." (PMID 38969910, 2024). "Interestingly, most of these proteins are ECM molecules and contribute to the invasiveness of glioma cells, including FN1, TNC, LAMC1, COL1A1, EGFR, CDK6, and COL6A2." (PMID 37059730, 2023). "In addition, the data on the survival rate of patients with glioma from the REMBRANDT study and TCGA GBM databases showed that high expressions of LOX and COL1A1 correlated with low survival rate." (PMID 35908277, 2022). "Furthermore, although not correlating to response to irradiation, recent studies have shown that COL1A1, ITGA7, ITGB3, ITGB4, HMMR and IBSP upregulation confer low survival rate to glioma patients." (PMID 34211843, 2021). "In conclusion, the collagen genes (COL1A1, COL1A2, COL3A1, COL4A1, COL4A2, and COL5A2) could regulate the immunosuppressive microenvironment and be involved in the EMT process of glioma." (PMID 34034744, 2021). "Additionally, some studies showed that COL1A1, COL1A2, and COL4A1could regulate the immunosuppressive TME of glioma." (PMID 35069551, 2021). "COL1A1 has been shown to be involved in cell invasion, and MET is an important factor involved in a variety of processes that contribute to the malignancy of gliomas." (PMID 32604718, 2020). "Finally, by using gene correlation analysis, we found that the COL1A1, COL1A2, FN1, ITGA1, ITGB1, and ANXA1 genes may play a synergistic role in glioma patients." (PMID 35711921, 2022).
glioma (continued). "Importantly, we identified that 6 collagen genes (COL1A1, COL1A2, COL3A1, COL4A1, COL4A2, and COL5A2) could regulate the immunosuppressive microenvironment of glioma." (PMID 34034744, 2021).
lung carcinoma (34 papers, 2017 to 2025). "In lung cancer, COL1A1 higher expression has been linked to tumor invasiveness and poor patient prognosis." (PMID 38913913, 2024). "In conclusion, COL1A1 can be used as a novel diagnostic, prognostic, and chemoresistance biomarker for lung cancer." (PMID 34475986, 2021). "Then, we analyzed the association between the levels of COL1A1 in the serum of lung cancer patients and clinicopathologic parameters." (PMID 34475986, 2021). "COL1A1 genes could be regarded as novel diagnostic biomarkers that predict the progression of human lung cancer." (PMID 37853419, 2023). "Furthermore, our statistical analysis revealed that COL1A1 was associated with poor prognosis and chemoresistance of lung cancer." (PMID 34475986, 2021). "In our study, higher COL1A1 levels were significantly associated with shorter PFS, and overexpression of COL1A1 may predict a poor prognosis in advanced lung cancer patients." (PMID 34475986, 2021). "In addition, the area under the curve (AUC) of COL1A1 from TCGA data sets was 0.8672, supporting COL1A1 as a diagnostic and prognostic marker in lung carcinoma." (PMID 33850663, 2021). "The levels of COL1A1 mRNA expression in lung cancer are increased and are significantly correlated with tumor diameter, metastasis, and OS." (PMID 36052170, 2022). "To investigate the potential significance of COL1A1 expression, we divided the TCGA lung cancer cohort (n = 1003) into COL1A1-high and low expression groups that were performed to evaluate the prognostic value." (PMID 33850663, 2021). "Here, we aimed to evaluate the level of COL1A1 in lung cancer samples and correlate its level with the clinical outcome." (PMID 34475986, 2021). "In the present study, we found that the COL1A1 level was significantly elevated in lung cancer tissues and serum samples, and it was closely associated with poor PFS and chemoresistance of lung cancer." (PMID 34475986, 2021). "Based on our previous bioinformatics analysis, genetic alterations of the extracellular matrix protein COL1A1 are likely to be a frequent event in human lung cancers." (PMID 34475986, 2021). "Our ELISA analysis revealed that the clinical significance of the serum level of COL1A1 in lung cancer patients was consistent with lung cancer tissues." (PMID 34475986, 2021). "High COL1A1 expression was associated with poor progression-free survival (PFS) and chemoresistance in lung cancer patients (P < 0.05)." (PMID 34475986, 2021). "In our experimental data, COL1A1 was highly expressed in human lung cancer tissues and was correlated with some clinicopathologic parameters, such as the occurrence of lymph nodes and distant metastases." (PMID 34475986, 2021). "The results showed that the COL1A1 gene copy number increased in lung cancer tissues compared to normal lung tissues in the Weiss lung dataset." (PMID 34475986, 2021). "To further evaluate the clinical utility of COL1A1 as the intrinsic chemoresistance serum marker, we analyzed the serum COL1A1 levels in 100 lung cancer patients using ELISA." (PMID 34475986, 2021). "To examine the correlation between COL1A1 expression and clinicopathologic factors in lung cancer, we evaluated its expression in lung cancer tissues by IHC." (PMID 34475986, 2021). "The result showed that the serum levels of COL1A1 in lung cancer patients were significantly higher than those in the healthy group (32.90 ± 8.08 ng/ml vs. 21.51 ± 6.16 ng/ml, P < 0.001)." (PMID 34475986, 2021). "We also observed upregulation of the COL1A1 mRNA level in lung cancer tissues compared with normal lung tissues in the Rohrbeck Lung dataset." (PMID 34475986, 2021). "In the IHC group, the PFS time of lung cancer patients with COL1A1-positive expression was markedly shorter than in the patients with COL1A1-negative expression." (PMID 34475986, 2021). "Based on GSE31210, GSE3141 and TGA databases, it is shown that COL1A1 is closely related to the prognosis of lung cancer patients." (PMID 33850663, 2021).
lung carcinoma (continued). "To investigate the potential of COL1A1 as a serological marker for lung cancer, we analyzed the level of COL1A1 in serum from lung cancer patients (n = 100) and healthy individuals (n = 40) by ELISA." (PMID 34475986, 2021). "Previous studies have shown that COL1A1 promotes airway epithelial cells to develop a mesenchymal cell phenotype in lung cancer." (PMID 32171282, 2020). "Analyzing the expression patterns of CAF markers in lung cancer tissues compared to normal tissues, we found that COL1A1, COL1A2, and FAP were significantly upregulated, indicating their potential as markers for identifying malignancies and metastatic diseases." (PMID 39034310, 2024). "Further in lung cancer tissues, through scRNA analysis at “IMMUcan SingleCell RNAseq-Database” of lung cancer, for the first time, we proved the specificity of COL1A1, COL1A2, and FAP, all of three are highly enriched in subgroup of CAF, the cluster of which was circled." (PMID 39034310, 2024). "Therefore, studying the role of prolidase, CREB3L1, and COL1A1 gene expression in lung cancer appears to be significant." (PMID 37508851, 2023). "Whereas, in contrast to CSCC, the higher expression of COL1A1 could promote lung cancer and mesothelioma progression via immune infiltration mechanisms (including CD4+ T cells, macrophage, neutrophil, and dendritic cell)." (PMID 36085041, 2022). "In conclusion, the present study screened 46 DEMs in GSE17681 and 1029 DEGs in GSE18842 and identified six hub genes related to lung cancer, including mTOR, NF1, CHD7, ETS1, IL-6, and COL1A1, which might be potential targets for lung cancer." (PMID 36211008, 2022). "It is found that COL1A1 can promote the occurrence of lung cancer." (PMID 33968130, 2021). "In our study, COL1A1 could be used as a predictive biomarker for chemoresistant patients with advanced lung cancer in first-line chemotherapy." (PMID 34475986, 2021). "Besides, Kaplan–Meier Plotter also showed a high COL1A1 expression closely correlated with the over-all survival and the progression-free survival of lung cancer patients." (PMID 33850663, 2021). "In addition, the serum levels of COL1A1 in lung cancer patients before chemotherapy were significantly higher than in patients after four cycles of chemotherapy (32.67 ± 5.84 ng/ml vs. 19.98 ± 3.95 ng/ml, P < 0.001)." (PMID 34475986, 2021). "High COL1A1 expression was observed in lung cancer tissues and serum (P < 0.05), it was significantly correlated with the peripheral type tumor, the larger diameter of the tumor, the occurrence of lymph node metastases and distant metastases, a higher TNM stage, and smoking (P < 0.05)." (PMID 34475986, 2021). "In addition, we demonstrate in lung cancer cell lines exposed to hypoxia or oxidative stress that COL1A1 transcription significantly responds to oxygen depletion, while other genes showed the modest upregulation in stress conditions." (PMID 28258342, 2017). "However, little is known about the clinical role of COL1A1 in lung cancer." (PMID 34475986, 2021). "However, the clinical significance of COL1A1 expression in lung cancer samples remains largely unknown." (PMID 34475986, 2021). "The markers of COL1A1, COL1A2, and FAP are significantly highly expressed in lung cancer, compared to normal tissues, while PDGFRA, PDGFRB, and ACTA2 either failed to be differentially expressed in cancer tissues, or were expressed in relative lower levels." (PMID 39034310, 2024). "In lung cancer stromal cells, FAP, COL1A1, and COL1A2 exhibited high sensitivity and specificity, reflecting the abundance of fibroblasts and CAFs." (PMID 39034310, 2024). "COL1A1, ACTA2, and alpha-SMA are relatively grouped in lung tissues, and PDGFRA, VCAM1 are expressed in both lung tissues and lung cancer cell lines, showing less specificity." (PMID 39034310, 2024).
lung carcinoma (continued). "We established targeted repression of UCHL1 expression in the lung cancer cell line H1299 and showed that UCHL1 directs the expression of the extracellular matrix genes COL1A1 and fibronectin." (PMID 38016026, 2023). "COL1A1, an ECM member, is an independent prognostic factor that promotes EMT in lung cancers via the TGF-β1 signaling pathway." (PMID 37626065, 2023). "So far, increasing numbers of studies have demonstrated that the expression of collagen family members, such as COL1A1 and COL1A2, was abnormal in several cancers, such as breast and lung cancers." (PMID 35426219, 2022). "Further verification found that six hub genes were screened in relation to lung cancer, including mTOR, NF1, CHD7, ETS1, IL-6, and COL1A1." (PMID 36211008, 2022). "Six hub genes were screened in relation to lung cancer, including mTOR, NF1, CHD7, ETS1, IL-6, and COL1A1." (PMID 36211008, 2022). "In previous microarray analyses, COL1A1 and UCP2 were found upregulated in various malignant tissues, including lung cancer." (PMID 28258342, 2017). "Notably, the newly identified markers, COL1A1 and COL1A2, stand out as versatile tools for CAF identification, survival prognosis, and the evaluation of treatment responses in lung cancer patients." (PMID 39034310, 2024). "The present study identified six hub genes that were related to lung cancer, including mTOR, NF1, CHD7, ETS1, IL-6, and COL1A1, which might be a potential target for lung cancer." (PMID 36211008, 2022). "In addition, six hub genes that were related to lung cancer were identified as hub genes, including mTOR, NF1, CHD7, ETS1, IL-6, and COL1A1." (PMID 36211008, 2022). "Furthermore, we analyzed the correlation of the expression of hub gene in lung cancer tissues, of which PECAM1, VWF, CD34, COL1A1, MMP9 and TIMP1 are closely related." (PMID 33850663, 2021). "Currently, in lung cancer cells, the role of COL1A1 is not sufficiently understood." (PMID 34475986, 2021). "Currently, in lung cancer, the clinical role of COL1A1 is not sufficiently understood." (PMID 34475986, 2021). "The expression of both COL1A1 and fibronectin decreased upon co-treatment of TGF-β1 and LDN57444, but this phenomenon was only observed in the lung cancer epithelial cell line H1299, and not in the human normal lung epithelial cell line BEAS-2B." (PMID 38016026, 2023).
cardiac hypertrophy (30 papers, 2013 to 2025). "For example, increased expression of Col1a1 and Col1a2, which encode for components of type I collagen, has been linked to remodeling of the cardiac matrix, and upregulation of collagen 1 is a well-established marker of cardiac fibrosis and is observed after cardiac hypertrophy." (PMID 35236346, 2022). "The mRNA levels of genes related to cardiac hypertrophy (Anp, Bnp, and Myh7) and fibrosis (Col1a1, Col3a1, and Ctgf) were upregulated in AAV‐TEAD1‐K177R mice." (PMID 38225750, 2024). "Markers for pathologic cardiac hypertrophy (Anp), fibrosis (Col1a1, Col3a1, and Galectin-3), and inflammation (Cox2 and Tnf-α) were also assessed." (PMID 36986490, 2023). "Increased collagen deposition is related to enhanced cardiac Col1a1 expression in the cardiac hypertrophy model." (PMID 35719043, 2022). "The function of YB-1 as a suppressor of COL1A1 is abolished, and the expression of Col1a1 is increased and promotes the development of cardiac hypertrophy." (PMID 34344446, 2021). "COL1A1, an important marker for cardiac hypertrophy and pathological remodeling, increased significantly in RFP heart." (PMID 27494843, 2016). "Reactive oxygen species (ROS) have been shown to up-regulate expression of profibrotic genes, such as col2a1, col1a1, and fn1, thereby resulting in direct extracellular matrix deposition in a transgenic mouse model, and resulting in cardiac hypertrophy." (PMID 23922799, 2013). "TAC‐induced myocardial hypertrophy and cardiac fibrosis were also attenuated upon HIPK1 knockdown, accompanied with reduced expression of pathological hypertrophy marker genes (ANP, BNP, and β‐MHC) and fibrosis‐associated genes (Col1a1, Col3a1, and CTGF)." (PMID 37098980, 2023). "Furthermore, it also suppressed the expression of fibrosis markers COL1A1, CTGF, and uPA and downregulated cardiac-hypertrophy-associated markers such as calcineurin, NFATC3, GATA4, pGATA4 and BNP." (PMID 35890118, 2022). "Col1a1 and col3a1 are closely related to the formation of myocardial hypertrophy." (PMID 36046382, 2022). "Further evidence of the development of cardiac hypertrophy and cardiomyopathy in Mrps5cKO mice includes the upregulation of the hypertrophy and disease marker genes (Nppa, Nppb, and Myh7) and fibrosis marker genes (Col1a1, Col1a2, and Col1a3) in Mrps5cKO hearts." (PMID 36949106, 2023). "In cardiac hypertrophy and the fibrotic response, the JAK2–STAT3 signaling pathway activates TGFB, COL1A1, and MYH7 transcription, contributing to cardiac remodeling and dysfunction." (PMID 39349833, 2024). "At protein level, H3L overexpression upregulated expression levels of cardiac hypertrophy marker (NPPB) and cardiac fibrosis markers (COL1A1 and COL3A1)." (PMID 39168969, 2024). "According to previous studies, collagen fibers COL1A1 and COL3A1 play an important role in cardiac hypertrophy." (PMID 36091816, 2022). "Among hypertrophy-related genes (ANP, BNP, β-MyHC, COL1A1), only BNP mRNA levels significantly increased (1.9-fold; p < 0.01), while CYP4B1 expression was suppressed, suggesting its inhibitory role in cardiac hypertrophy." (PMID 40924729, 2025). "Furthermore, at the protein level, the overexpression of H3L substantially increased the expression levels of cardiac hypertrophy markers (NPPB) and cardiac fibrosis markers (COL1A1 and COL3A1)." (PMID 39168969, 2024). "Furthermore, real‐time PCR results suggested that NLRP3 deletion suppressed the expression of cardiac hypertrophy‐related genes (ANP, BNP, and Myh7) and cardiac fibrosis‐related genes (Col1a1 and CTGF) in obese hearts." (PMID 39604027, 2024). "In addition, EVO preserves mitochondrial function by increasing the activity of the PGC1α/NRF1/TFAM signaling pathway and inhibits the development of cardiac hypertrophy and fibrosis by attenuating TGFβ/IGFBP7/Col1a1 expression." (PMID 37009790, 2023).
cardiac hypertrophy (continued). "Next, we measured genes typically upregulated in pathological cardiac hypertrophy: genes regulating collagen synthesis (Col1a1, Col3a1, Col8a1, and Ccl2) were not altered by diet." (PMID 35736495, 2022). "Further supporting this, the observed reduction in HFD-induced fibrotic gene expression (Col1a1, Col3a1, Mmp9) by SAAR suggests a protective effect against the abnormal remodeling of the extracellular matrix that normally accompanies pathological cardiac hypertrophy." (PMID 39770968, 2024). "Using qPCR, we found that the expression of ANP, BNP, COL1A1, and COL4A1 mRNA in cardiomyocytes following COX6A2 knockdown was significantly increased compared with that of the WT cells, suggesting that the cardiomyocytes developed toward cardiac hypertrophy and fibrosis." (PMID 38072986, 2023). "In our study, an increase of col1a1 gene expression and collagen type 1 fibers were observed in the PAH cardiac hypertrophy phase in PAH; this effect was not dependent on exercise." (PMID 34495964, 2021).